RPE65 (retinoid isomerohydrolase RPE65)
Diseases named in the same sentence as RPE65 in open-access papers (continued):
Sharing a sentence is not in itself a finding about the gene and the disease.
Blindness (30 papers, 2007 to 2025). Blindness is the condition of lacking visual perception defined as a profound reduction in visual perception. "The RPE65 gene is subject to many mutations which give rise to the early onset severe blinding disorder Leber congenital Amaurosis type 2 (LCA2)." (PMID 36265895, 2023). "Patients with RPE65-associated IRDs often present with severe vision impairment or blindness, nystagmus and night blindness from an early age." (PMID 37892166, 2023). "Does severe early visual deficit in humans with RPE65 mutations lead to atrophy of the orbital optic nerves and thinning of occipital lobe gray and white matter as reported in forms of early blindness ?" (PMID 17594175, 2007). "The results indicated that modified liposome showed effective Rpe65 gene delivery in a specific and further alleviated long-term expression of the Rpe65 gene in Rpe65 knockout mice, resulting inthe rectification of blindness in vivo." (PMID 35200463, 2022). "However, Briard dogs express a common mutation of the Rpe65 gene, which has also been shown to cause LCA in humans and thus, can be used as a model of human blindness." (PMID 34693516, 2022). "An exciting application of the Briard dog model in human blindness is its use as an experimental platform for investigating gene therapy, involving the injection of wild type Rpe65 gene encapsulated in a viral vector, such as the adeno‐associated virus type 2 (AAV2), into the eye." (PMID 34693516, 2022). "We might consider that there exists systematically different brain structure in either RPE65 mutants specifically or animals with congenital blindness generally." (PMID 23284904, 2012). "There is some variability in the descriptions of the phenotype of young Rpe65-deficient dogs, most notably with respect to visual function, with some authors describing diminished vision only in dim light, while others report blindness irrespective of lighting conditions." (PMID 33435495, 2021). "–4 Biallelic mutations in RPE65 are often associated with a rare form of inherited retinal degeneration (RPE65-IRD) with progressive atrophy of the RPE and the photoreceptors together with severe vision impairment to blindness." (PMID 39745677, 2025). "RPE65, an isomerohydrolase exclusively located in the RPE that produces 11-cis-retinol from all-trans-retinyl esters, is a key player in the visual cycle whose alterations lead to irreversible blindness." (PMID 34864827, 2021). "We showed for the first time that LPD promotes efficient delivery in a cell specific-manner and long-term expression of the Rpe65 gene in mice lacking Rpe65 protein, leading to in vivo correction of blindness." (PMID 26062170, 2015). "The results revealed that LPD could encourage effective gene delivery in a cell specific manner and achieve the long-term expression of Rpe65 gene to Rpe65-lacking mice, thus inducing blindness correction in vivo." (PMID 38926780, 2024).
Leber congenital amaurosis type 2 (24 papers, 2011 to 2025). "Gene editing technologies have achieved significant results in repairing the Rpe65 gene mutation associated with the hereditary retinal disease Leber congenital amaurosis type 2 (LCA2)." (PMID 39707395, 2024). "Mutation of the RPE65 allele has been found to destroy optic cells and cause clinical manifestations of Leber congenital amaurosis type 2 (LCA2) and early-onset retinal dystrophy, eventually leading to complete blindness." (PMID 34393803, 2021). "AAV2-vectors encoding RPE65 demonstrated a robust safety profile following subretinal delivery in human clinical trials for Leber congenital amaurosis type 2." (PMID 33589779, 2021). "The Rpe65-deficient dog has been important for development of translational therapies of Leber congenital amaurosis type 2 (LCA2)." (PMID 33435495, 2021). "Mutations in RPE65 (retinoid isomerohydrolase RPE65) are a cause of severe childhood-onset visual impairment known as Leber congenital amaurosis type 2 (LCA2)." (PMID 40461693, 2025). "Specifically, we used the Pde6βRd10 (rd10) and RhoP23H/WT (P23H) mouse models of autosomal recessive and autosomal dominant RP, respectively, as well as the Rpe65−/− mouse model of Leber’s congenital amaurosis type 2 (LCA2)." (PMID 39389360, 2024). "LuxturnaTMreceived FDA approval in December 2017 to treat Leber congenital amaurosis type 2 (LCA2), which is an inherited retinal disease (IRD) caused by mutations in the RPE65 gene, leading to severely impaired vision at birth." (PMID 35652098, 2022). "The most widely accepted success of adeno-associated virus (AAV) vector-mediated ocular gene replacement is for treatment of Leber’s congenital amaurosis 2 (LCA2), a rare retinal disease due to mutations in the RPE65 gene." (PMID 32123325, 2021). "Inherited retinopathies such as Leber congenital amaurosis type 2 (LCA2), which is associated with mutations in the RPE65 gene, have been the focus of early clinical interest and success." (PMID 30591984, 2018). "There are no specific treatments available for retinal degenerations, except a recently approved gene therapy for RPE65 related Leber’s congenital amaurosis type 2 (LCA2; Food and Drug Administration, 2017)." (PMID 29687079, 2018).
choroideremia (18 papers, 2016 to 2025). Choroideremia (CHM) is an X-linked chorioretinal dystrophy characterized by progressive degeneration of the choroid, retinal pigment epithelium (RPE) and retina. "Despite the marginal improvement of vision and the variability of outcomes between trials, the promising results of the early clinical trials in the management of choroideremia highlight the prospects for genetic therapy in diseases beyond RPE65 mutation-mediated LCA." (PMID 35467460, 2022). "AAV vector-based gene therapy has obtained the marketing approval for treating RPE65-associated LCA, Leber hereditary optic neuropathy (LHON), and choroideremia (CHM)." (PMID 36463195, 2022). "The development of current gene therapy for inherited retinal diseases in clinical trials, including RPE65-mediated inherited retinal dystrophy and choroideremia, requires the delivery of the viral vector safely into the subretinal space." (PMID 33510949, 2021). "Localized iatrogenic detachment of degenerate retina has been performed for the subretinal delivery of adeno-associated viral gene therapy vectors for RPE65 and MERTK-associated RP,24, 25, 26, 27 and choroideremia." (PMID 29110946, 2018). "We suggest that cases of choroideremia with negative CHM sequencing should be tested for this RPE65 variant." (PMID 33776059, 2021). "The disease phenotype is comparatively much milder than RPE65-LCA and closely resembles the clinical manifestations of choroideremia." (PMID 31963381, 2020). "The observation of one pedigree in which two IRDs are segregating (RPE65-RP and CHM-Choroideremia) serves to emphasise the essential role that NGS will play in the future diagnosis of this genetically heterogeneous group of conditions." (PMID 27624628, 2016).
night blindness (13 papers, 2010 to 2023). Inability to see clearly in dim light. "Patients with LCA who harbor RPE65 mutations exhibit a deficiency in photoreceptor rhodopsin, leading to severe night blindness and visual impairment following birth." (PMID 38264046, 2023). "Most children with RPE65 deficiency have an EOSRD phenotype with profound night blindness from birth but residual cone-mediated vision and often mild if any nystagmus." (PMID 28689169, 2017). "Since RPE65 mutations in RPE affect rod function even at earliest disease stages, patients typically suffer from severe night blindness and severely reduced visual acuity and abnormal eye movements (nystagmus) from an early age on." (PMID 36672611, 2022). "Luxturna® treatment delivers a functional copy of the RPE65 gene to the retina of patients suffering from severe night blindness (nyctalopia)." (PMID 36463195, 2022). "In RP, mutations in the gene, RPE65, result in the disruption of the RPE65 protein production in the retinal pigment epithelium (RPE), leading to worsened vision, night blindness, and decreased peripheral vision." (PMID 35395806, 2022). "Symptoms of night blindness were reported by 11 individuals, including CRB1 or TULP1 mutations (all individuals; three each group), RPGRIP1 or RPE65 mutations (two individuals each) and RDH12 mutations (one individual)." (PMID 29178642, 2017). "The spectrum of RPE65-mediated IRD exhibits common clinical findings, initially characterised by nyctalopia (night blindness), present from early childhood and due to a primary effect on the rod photoreceptors." (PMID 34088339, 2021). "In the patient 10–33 a 6-year-old boy with a reduction of visual acuity to the level of counting fingers, night blindness, astigmatism, and myopia NGS panel for LCA genes revealed a homozygous substitution c.304G>T in exon 4 (p.Glu102*) in the RPE65 gene." (PMID 33308271, 2020).
spinal muscular atrophy (9 papers, 2020 to 2024). A motor neuron disease that affect the muscles, and characterized by muscle weakness and atrophy resulting from progressive degeneration and irreversible loss of the anterior horn cells in the spinal cord (i.e., lower motor neurons) and the brain stem nuclei. "Indeed, virus-mediated gene therapies have now been approved by the FDA in the US for RPE65-associated retinal dystrophy (voretigene neparvovec marketed as Luxturna) and SMN1-linked spinal muscular atrophy (SMA; onasemnogene abeparvovec marketed as Zolgenmsa), as well as non-neuronal conditions." (PMID 32765219, 2020).
achromatopsia (6 papers, 2020 to 2024). Achromatopsia (ACHM) is a rare autosomal recessive retinal disorder characterized by color blindness, nystagmus, photophobia, and severely reduced visual acuity due to the absence or impairment of cone function. "Stationary IRDs constituted 14.2% (3.1% albinism, 4.7% CSNB, 5.4% achromatopsia), variants causative for LCA were assigned to 8.5% (CEP290, GUCY2D, RDH12, CREB1, RPE65, RD3), 6% were annotated in RS1, and 3.1% were annotated in CHM." (PMID 39596324, 2024). "Of 19 diseases, 10 had >10 participants: ABCA4 retinopathy; CNGB3- and CNGA3-associated achromatopsia; RPGR-associated disease; RPE65-associated disease; blue cone monochromacy (BCM); Bornholm eye disease (BED); TYR- and OCA2-associated oculocutaneous albinism; and GPR143-associated ocular albinism." (PMID 35704304, 2022).
Leber hereditary optic neuropathy (6 papers, 2017 to 2025). Leber's hereditary optic neuropathy (LHON) is a mitochondrial neurodegenerative disease affecting the optic nerve and often characterized by sudden vision loss in young adult carriers. "Notably, NR082 targets Leber’s hereditary optic neuropathy (LHON) caused by ND4 mitochondrial gene mutation; BBM-H901 delivers hFIX Padua cDNA to treat Hemophilia B; and LX101 employs rAAV2-RPE65 to cure RPE65-associated inherited retinal degeneration." (PMID 40179116, 2025).
Nystagmus (6 papers, 2010 to 2023). Rhythmic, involuntary oscillations of one or both eyes related to abnormality in fixation, conjugate gaze, or vestibular mechanisms. "The advertised advantage of RPE65 gene therapy was the improvement of nystagmus; however, nystagmus in two patients who suffered from high-amplitude nystagmus showed no resolution." (PMID 33926102, 2021).
Rod-cone dystrophy (6 papers, 2009 to 2025). An inherited retinal disease subtype in which the rod photoreceptors appear to be more severely affected than the cone photoreceptors. "Previous reports indicate that mutations in the RPE65 gene also lead to milder forms of late-onset and progressive rod-cone dystrophy, in contrast to mutations in other genes associated with LCA." (PMID 38264046, 2023). "This RPGRIP1-deficient model is an attractive alternative LCA canine model in the sense that, in contrast to RPE65, it is not a rod-cone dystrophy but a cone-rod dystrophy and that the cells to target are not the RPE but the photoreceptors." (PMID 19223988, 2009).
early-onset retinal dystrophy (5 papers, 2009 to 2025). "A 12-year-old girl, diagnosed with RPE65-related early-onset retinal dystrophy (EORD), was referred to Ghent University Hospital at the age of 4 years." (PMID 40757766, 2025). "As for the described mutations in RPE65, affected patients with mutations in the gene encoding the lecithin retinol acyl transferase (LRAT) develop severe early-onset retinal dystrophy." (PMID 19672311, 2009).
Atrophy (4 papers, 2007 to 2025). Any weakening or degeneration, especially through lack of use. "The metabolic effect-based hypothesis is corroborated by the evidence of a greater improvement in the FST results in the atrophy group suggesting that RPE65 overexpression might drive atrophy development, as highlighted by the German-American cohort of 71 eyes." (PMID 38627549, 2024). "Looking at the history of VN tolerability through the lens of SRV, it is noteworthy that the preclinical VN studies in RPE65−/− Briard dogs and NHPs42 in which no retinal thinning and atrophy were reported used smaller SRVs of 100-200 μL, compared to a larger SRV of 300 μL in human patients." (PMID 41230903, 2025).
congenital stationary night blindness (4 papers, 2012 to 2025). "RPE65 and RLBP1, which were highly and specifically expressed in the P4 cluster, are susceptible genes contributing to RP and congenital stationary night blindness (CSNB)." (PMID 34977041, 2021). "Of note, other RPE65-IRD phenotypes that exhibit little or no progression, akin to those associated with congenital stationary night blindness, may warrant a more conservative approach, as we do not know whether treatment would provide benefits in these scenarios." (PMID 40757766, 2025).
myopia (4 papers, 2020 to 2025). "Previous studies have shown that myopia is associated with the RPE65 mutation." (PMID 38662103, 2024). "However, in our cohort, all four patients with RPE65 variants had hyperopia, and in contrast, two of 14 patients with RPGRIP1 variants had myopia." (PMID 38662103, 2024).
autosomal dominant retinitis pigmentosa (3 papers, 2012 to 2024). Autosomal dominant retinitis pigmentosa (RP) is an autosomally dominant inherited retinal dystrophy leading to progressive loss of the photoreceptors and retinal pigment epithelium and resulting in blindness usually after several decades. "Specifically, we analyzed retinal samples from Pde6βRd10 and RhoP23H/WT (in short, rd10 and P23H) mouse models of autosomal recessive and autosomal dominant retinitis pigmentosa (RP), respectively; and samples from the Rpe65−/− mouse model of LCA2." (PMID 39389360, 2024). "As mutation in the RPE65 gene may be related to LCA, severe early childhood onset retinal dystrophy, or even autosomal-dominant retinitis pigmentosa, different enrollment criteria may generate different positive results." (PMID 22509104, 2012).
autosomal recessive retinitis pigmentosa (3 papers, 2012 to 2023). Autosomal recessive retinitis pigmentosa (RP) is an autosomally recessive inherited retinal dystrophy leading to progressive loss of the photoreceptors and retinal pigment epithelium and resulting in blindness usually after several decades. "In 2017, the Food and Drug Administration (FDA) approved a medication for gene therapy in patients with autosomal recessive retinitis pigmentosa caused by biallelic pathogenic variants in the RPE65 gene." (PMID 38002999, 2023).
diabetes (3 papers, 2018 to 2023). "Ret-NH2 (retinylamine) inhibits RPE65, an enzyme involved in the visual cycle, and has been shown to reduce diabetes-induced effects related to oxidative stress." (PMID 30373222, 2018).
Usher syndrome (3 papers, 2022 to 2025). A syndromic diseae characterized by the association of sensorineural deafness (usually congenital) with retinitis pigmentosa and progressive vision loss. "Turning to USH (Usher syndrome) patients with an RPE65-related condition, it might be worthwhile to focus on targeted gene therapy studies for those who display OCT scans featuring intact photoreceptors and partially preserved residual photoreceptor function at early disease stages." (PMID 37762059, 2023).
age-related macular degeneration (2 papers, 2021). Age-related loss of vision in the central portion of the retina (macula), secondary to retinal degeneration. "In this study, we investigated the time course and spatial recruitment of systemically administered RPE65-programmed BMDC to the retina in a mouse model of age-related macular degeneration (AMD)." (PMID 34357416, 2021). "Cell replacement for age-related macular degeneration (AMD) and gene therapy for RPE65 are recent successful examples." (PMID 33510949, 2021). "Previously, we reported that the intravenous injection of bone marrow-derived cells (BMDC) infected with lentivirus expressing the human RPE65 gene resulted in the programming of BMDC to promote visual recovery in a mouse model of age-related macular degeneration (AMD)." (PMID 34357416, 2021).
albinism (2 papers, 2022 to 2024). A congenital disorder characterized by partial or complete absence of melanin pigment in the eyes, hair, or skin. "Significant odds for a short AL were seen for GPR143-associated ocular albinism (adjusted OR, 56.20; P < 0.001), TYR-associated albinism (adjusted OR, 34.19; P < 0.001), and RPE65-associated disease (adjusted OR, 12.52; P < 0.01)." (PMID 35704304, 2022). "Significantly increased odds of a longer AL (≥26 mm) were observed for BCM and BED and also (but to a lesser extent) for TYR- and OCA2-associated albinism, as well as for RPE65- and RPGR-associated disease." (PMID 35704304, 2022).
autoimmune uveitis (2 papers, 2012 to 2024). An autoimmune form of uveitis (disease). "Another reason for considering RPE65 an attractive protein for further research in ERU is the fact that immunoreactions against RPE65, next to CRALBP and S-Antigen, are known to induce experimental autoimmune uveitis in rats." (PMID 23203049, 2012).
cone dystrophy (2 papers, 2017 to 2025). An inherited ocular disorder characterized by the loss of cone cells, the photoreceptors responsible for both central and color vision. "The dependence of cone PR survival on RPE65 was reported previously; therefore, the direct regulation of RPE65 by ERK1/2 could account, at least in part, for the severe cone dystrophy found in RPE-DKO mice." (PMID 29038159, 2017).
melanoma (2 papers, 2022). A malignant, usually aggressive tumor composed of atypical, neoplastic melanocytes. "RPE65 was shown to be expressed by nevi, but downregulated in melanoma." (PMID 35269844, 2022). "RPE65 was demonstrated to be highly downregulated in melanoma and squamous cell carcinoma of skin." (PMID 36134028, 2022). "Our in silico analysis of IFN-treated melanoma tissues of TCGA revealed the differential expression of five members of our 79 IFN-res DEGs in IFN-treated melanoma tissues: IRG SOX4 and non-IRGs WFDC1, BCAN, RPE65, and MAPT." (PMID 35269844, 2022).
neovascular age-related macular degeneration (2 papers, 2024). "However, transdifferentiated RPE cells occasionally express RPE65 in several pathological conditions of the retina, including fibrotic scars of neovascular age-related macular degeneration and the subretinal membrane of proliferative vitreoretinopathy." (PMID 38892233, 2024).
Retinal atrophy (2 papers, 2024 to 2025). A nonspecific term denoting wasting, especially as a result of degeneration, of the retinal pigment epithelium (RPE) and neurosensory retinal cells. "Retinal atrophy has also been described after treatment with voretigene neparvovec for RPE65-RD yet was not preceded by hyperpigmentation and developed progressively within 3 months post-treatment, suggesting a different causal mechanism than that observed in our trial." (PMID 39256350, 2024).